ITM2B (integral membrane protein 2B)
Description:
Plays a regulatory role in the processing of the amyloid-beta A4 precursor protein (APP) and acts as an inhibitor of the amyloid-beta peptide aggregation and fibrils deposition. Plays a role in the induction of neurite outgrowth. Functions as a protease inhibitor by blocking access of secretases to APP cleavage sites. Mature BRI2 (mBRI2) functions as a modulator of the amyloid-beta A4 precursor protein (APP) processing leading to a strong reduction in the secretion of secretase-processed amyloid-beta protein 40 and amyloid-beta protein 42. Bri23 peptide prevents aggregation of APP amyloid-beta protein 42 into toxic oligomers.
Synonyms: imBRI2; Bri; BRI2; E25B; E3-16; BRICD2B; ABRI; FBD; RDGCA
Tractability: Antibody: UniProt places it where antibodies can reach, with high confidence; its Gene Ontology location is reachable by antibodies, with high confidence; UniProt predicts a signal peptide or a membrane-spanning region. PROTAC: ubiquitination databases record sites on it; its protein half-life has been measured.
Gene: Protein-coding gene on chromosome 13 (48,232,612 to 48,270,357, forward strand). Ensembl gene ENSG00000136156.
Subcellular location: Golgi apparatus membrane (Integral membrane protein 2B); Cell membrane (BRI2, membrane form); Endosome membrane; Secreted (Bri23 peptide); Secreted (BRI2C, soluble form)
Subcellular location (Human Protein Atlas): Golgi apparatus; Vesicles; Predicted to be secreted
Pathways (Reactome):
Metabolism of proteins: Amyloid fiber formation
Gene Ontology:
Molecular function: amyloid-beta binding; protein binding; ATP binding
Biological process: negative regulation of amyloid precursor protein biosynthetic process; nervous system development
Cellular component: endosome membrane; extracellular exosome; extracellular region; Golgi apparatus; Golgi membrane; Golgi-associated vesicle membrane; membrane; organelle membrane; plasma membrane
Genetic constraint (gnomAD): Loss-of-function variants: 5 observed, 14.33 expected, observed/expected ratio (o/e) 0.35, 90% interval 0.18 to 0.73. The upper end of that interval is the gene's LOEUF score, 0.73, which puts it in group 3 of 6, group 1 being the genes least tolerant of losing a copy. Missense variants: 206 observed, 213.69 expected, observed/expected ratio (o/e) 0.96, 90% interval 0.86 to 1.08. Synonymous variants: 84 observed, 75.13 expected, observed/expected ratio (o/e) 1.12, 90% interval 0.94 to 1.34.
Homologues: Orthologues: chimpanzee ITM2B (100% identical), macaque ITM2B (100% identical), rabbit ITM2B (97% identical), rat Itm2b (96% identical), dog ITM2B (96% identical), mouse Itm2b (95% identical), pig ITM2B (95% identical), guinea pig ITM2B (82% identical), tropical clawed frog itm2b (70% identical), zebrafish itm2ba (59% identical), zebrafish itm2bb (57% identical), Drosophila melanogaster CG3662 (24% identical), and 1 more. Paralogues in human: ITM2C (44% identical), ITM2A (41% identical).
Diseases named in the same sentence as ITM2B in open-access papers:
ITM2B is named in the same sentence as 61 diseases in open-access papers, as found by Europe PMC text mining. Sharing a sentence is not in itself a finding about the gene and the disease. The quoted sentences say what the papers report.
dementia (45 papers, 2009 to 2026). Loss of intellectual abilities interfering with an individual's social and occupational functions. "On the other hand, mutations in BRI2 (encoding for ITM2B) have been used to model familial Danish dementia, a hereditary form of CAA." (PMID 41388472, 2025). "ITM2B/BRI2 mutations affecting its stop codon are associated with familial forms of dementia and deposits containing amyloid forms of the peptides which are generated upon stop-loss have been observed in vivo." (PMID 40314981, 2025). "Mutations in ITM2B (which encodes the BRI2 precursor protein) that are associated with rare familial Danish and British dementias resembling AD result in decreased BRI2 protein levels and, consequently, increased APP processing." (PMID 37307834, 2024). "Future work will expand these data via the use of genome editing to increase the number of lines with which to investigate mechanisms of FBD as well as expand investigations to other ITM2B-linked dementias." (PMID 39546024, 2024). "Its homolog BRI2 (ITM2B) is known to cause cerebral amyloid angiopathy in familial British and Danish dementias." (PMID 38713744, 2024). "Mutations in integral membrane protein 2B (ITM2b/BRI2) gene cause familial British and Danish dementia (FBD and FDD), autosomal dominant disorders characterized by progressive cognitive deterioration." (PMID 33172889, 2021). "Other differentially expressed genes have been previously associated with dementia (ITM2B, MAPT, ZNF267, and DHX37)." (PMID 34194426, 2021). "ITM2B encodes a transmembrane protein that helps to inhibit the accumulation of beta-amyloid, but mutations have been implicated in Familial British Dementia and Familial Danish Dementia with similar pathology to Alzheimer disease." (PMID 27535846, 2016). "ITM2B is therefore strongly associated with the neurodegenerative diseases, such as British and Danish Familial Dementia." (PMID 26274327, 2015). "Cases caused by APP/PSEN mutations are classified as FAD and those caused by mutations in BRI2/ITM2b as FDD or Familial British dementia (FBD)." (PMID 23451158, 2013). "Mutations in the integral membrane protein 2B, also known as BRI2, a type II trans-membrane domain protein cause two autosomal dominant neurodegenerative diseases, Familial British and Danish Dementia." (PMID 19924302, 2009). "In ITM2B, two stop codon disruptions associated with dementia yield amyloidogenic proteins elongated by 11 residues; duplication of 10 nucleotides between the penultimate and final translated codons in FDD, and a single base substitution in FBD." (PMID 19747390, 2009). "Mutations in ITM2B cause familial British, Danish, Chinese, and Korean dementias." (PMID 39546024, 2024). "ITM2B/BRI2 mutations cause Alzheimer’s Disease (AD)-related dementias." (PMID 38347225, 2024). "All pathogenic ITM2B/BRI2 mutations lead to amyloidogenic peptide accumulation, which is believed to cause neuronal damage and dementia similar to the amyloid hypothesis." (PMID 37733660, 2023). "To test this hypothesis, we studied glutamatergic neurotransmission in SC–CA3>CA1 synapses of mice carrying the pathogenic Danish and British dementia mutations (Itm2bD/D and Itm2bB/B mice) into the Itm2b mouse gene." (PMID 33172889, 2021). "Familial British dementia and familial Danish dementia are neurodegenerative disorders caused by mutations in the gene integral membrane protein 2B (ITM2b) encoding BRI2, which tunes excitatory synaptic transmission at both presynaptic and postsynaptic termini." (PMID 34416235, 2021). "In addition to APP, mutations in genes that regulate APP processing, such as PSENs and BRI2/ITM2B, cause dementias." (PMID 25247712, 2014). "Although dementias due to APP/PSEN1/PSEN2 mutations are classified as familial Alzheimer disease (FAD) and those due to mutations in BRI2/ITM2B as British and Danish dementias (FBD, FDD), data suggest that these diseases have a common pathogenesis involving toxic APP metabolites." (PMID 23217200, 2012).
dementia (continued). "Thus, to study familial Danish dementia (FDD) and familial British dementia (FBD), 15 years ago, we generated mice carrying the pathogenic Danish and British dementia mutations (integral membrane protein 2B [ITM2b]; Itm2bD and Itm2bB mice) into the Itm2b mouse gene." (PMID 34416235, 2021). "In addition to AD, the clinical relevance of this protein lies in two different autosomal dominant mutations in the ITM2B gene, which are associated with two rare early-onset forms of dementia, the Familial British and Danish dementias (FBD and FDD, respectively)." (PMID 29476059, 2018). "Stop-loss in ITM2B/BRI2 leads to the production of aberrant peptides that deposit as amyloids and cause different familial forms of dementia." (PMID 40314981, 2025). "In the last 3 y, two additional stop-loss mutations in ITM2B/BRI2 have been discovered, leading to Korean (FKD) and Chinese Dementia (FCD)." (PMID 40314981, 2025). "ITM2B, also known as BRI2, is instead mutated in familial British (FBD) and Danish Dementia (FDD) and also encodes amyloids upon stop-loss." (PMID 40314981, 2025). "Mutations in ITM2B (also known as BRI2) cause familial British, Danish, Chinese and Korean dementias (FBD, FDD, FCD, and FKD, respectively) and have also been associated with autosomal dominant retinal dystrophy." (PMID 39546024, 2024). "ITM2B/BRI2 mutations cause several autosomal dominant neurodegenerative diseases, including Familial Danish (FDD) and British (FBD) dementia that share similarities with AD, such as amyloid plaques and neurofibrillary tangles." (PMID 37733660, 2023). "Familial British dementia (FBD) and familial Danish dementia (FDD) are autosomal dominant forms of dementia caused by mutations in the integral membrane protein 2B (ITM2B, also known as BRI2) gene." (PMID 36102248, 2022). "In this context, it is worth mentioning that several genes linked to dementia, including APP, PSEN1, PSEN2, and ITM2b, play a physiological role in glutamatergic transmission and that mutations linked to familial dementia alter this physiological functions." (PMID 33434745, 2021). "All patients carrying variants in APP, CSF1R, ITM2B (p.Ile251Val), and NOTCH3 genes showed a family history for dementia." (PMID 33770234, 2021). "Mutations in the Integral membrane protein 2B (ITM2b/BRI2) gene, which codes for a protein called BRI2, cause familial British and Danish dementia (FBD and FDD)." (PMID 30890756, 2019). "Although mutations in APP and genes that regulate processing of APP, such as PSENs and BRI2/ITM2B, cause dementias, the normal function of APP in synaptic transmission, synaptic plasticity and memory formation is poorly understood." (PMID 25247712, 2014). "The prevailing pathogenic model for dementias caused by mutations in APP and genes that regulate APP processing (PSEN1, PSEN2 and BRI2/ITM2b) posits that amyloid peptides trigger dementia." (PMID 23217200, 2012). "Mutations in membrane protein 2B (ITM2B) have been identified as cause of dementias and complex neurodegenerative phenotypes with no reports on the proteome so far." (PMID 38687737, 2024). "ITM2B mutations have been linked to four autosomal dominant neurodegenerative diseases, the Familial British Dementia (FBD), the Familial Danish Dementia (FDD) and the newly discovered Familial Chinese and Familial Korean Dementias." (PMID 38347225, 2024). "Collectively referred to as chromosome 13 dementias, these conditions are associated with furin‐based processing of mutated integral membrane protein 2B (ITM2B, also known as BRI2) precursor protein, that results in the production of ABri or ADan amyloid peptides, respectively." (PMID 36102248, 2022). "Accumulation of ITM2b has been observed around amyloid plaques in neocortex and hippocampus of human AD cases, suggesting a shared mechanism between familial Danish/British dementia and AD, centered on amyloidosis." (PMID 30459560, 2018).
dementia (continued). "Based on the amyloid cascade hypothesis, transgenic mice carrying mutant APPPSEN1/2 or BRI2/ITM2b are used to model these dementias, as over-expression is necessary to reproduce amyloidosis." (PMID 22537414, 2012). "Stop-loss in ITM2B/BRI2 results in C-terminal extension of the encoded protein and, upon furin cleavage, in the production of two 34 amino acid long peptides, ADan and ABri, that accumulate as amyloids in the brains of patients affected by familial Danish and British Dementia." (PMID 40314981, 2025). "Our group reported a missense mutation in ITM2B, in an unusual retinal dystrophy with no dementia." (PMID 34446781, 2021). "One protein that binds to C99 and full-length APP via Aβ-Nt is integral membrane protein 2B (ITM2b/BRI2), the gene responsible for familial British and Danish dementia (FBD and FDD, respectively)." (PMID 36766796, 2023).
Alzheimer disease (23 papers, 2009 to 2026). A progressive, neurodegenerative disease characterized by loss of function and death of nerve cells in several areas of the brain leading to loss of cognitive function such as memory and language. "In addition, these findings further support the hypothesis, put forward several years ago10, that familial Danish, British and Alzheimer’s dementias share a pathogenic sameness and that Itm2b should be recognized as a fourth Familial Alzheimer disease gene." (PMID 30890756, 2019). "Returning to Alzheimer’s disease, the transcript ranked 26th most A + U enriched encodes the ITM2B (BRI2) protein, an inhibitor of amyloid precursor protein processing by secretases." (PMID 40341320, 2025). "In Alzheimer's disease, ITM2B, through its BRICHOS domain, participates in protein folding and prevents amyloid fibril formation." (PMID 39639394, 2024). "Together, Itm2b, Itm2c, Cst3 and Clu potentially ameliorate Alzheimer’s disease." (PMID 38017352, 2024). "Using NEBULA in Alzheimer’s disease cohort data sets, we found that the cell-level expression of APOE correlated with that of other genetic risk factors (including CLU, CST3, TREM2, C1q, and ITM2B) in a cell-type-specific pattern and an isoform-dependent manner in microglia." (PMID 34040149, 2021). "Of particular importance seems an increase in the content of two proteins playing a major role in the pathogenesis of Alzheimer’s disease: APP, a direct precursor of β-amyloid, and ITM2B (BRI2), which is a physiological suppressor of β-amyloid production." (PMID 27727329, 2016). "For example, ITM2B and PEN-2 are involved in the pathophysiology of Alzheimer’s disease in Homo sapiens characterized by plaque formation." (PMID 25786607, 2015).
amyloidosis (13 papers, 2009 to 2025). A disorder characterized by the localized or diffuse accumulation of amyloid protein in various anatomic sites. "Interestingly, the ITM2b protein, also called BRI2, was linked to the amyloidosis pathway and increased in Tg mice." (PMID 30459560, 2018).
familial Danish dementia (13 papers, 2011 to 2026). "Mutations in the BRI2 gene (also known as ITM2B), located on the long arm of chromosome 13, cause the autosomal dominant neurodegenerative diseases familial British dementia (FBD), familial Danish dementia (FDD), and Chinese dementia." (PMID 36436561, 2022). "Familial British Dementia (FBD) and Familial Danish Dementia (FDD) are autosomal dominant neurodegenerative disorders associated with mutations in the BRI2 gene on chromosome 13 (also named ITM2B)." (PMID 24405716, 2014). "The formation of protein aggregates is well-established as a source of toxic GOF, as observed in neurodegenerative disorders such as Parkinson’s disease, amyotrophic lateral sclerosis, and familial British dementia associated with ITM2B, as well as in systemic amyloidosis." (PMID 41556340, 2026). "Notably, ITM2B variants linked to familial Danish dementia and retinal dystrophy significantly attenuated the inhibition of GLUT9–mediated urate influx." (PMID 31695625, 2019). "Notably, we found that ITM2B mutants associated with familial Danish dementia (FDD) and FRD showed significantly attenuated inhibition of GLUT9-mediated urate influx." (PMID 31695625, 2019). "A mutation in the BRI2/ITM2b gene causes familial Danish dementia (FDD)." (PMID 22537414, 2012). "Furthermore, human genetic mutations which result in longer ITM2B protein C-terminal (and which increase the size and fibrillogenicity of the secreted peptide), are associated with two well-characterized neurogenerative diseases, familial British dementia and familial Danish dementia." (PMID 37674727, 2023). "Two types of mutation of Itm2b have been link to familial British Dementia (FBD) and familial Danish Dementia (FDD)." (PMID 24831988, 2014).
hypophysitis (11 papers, 2020 to 2025). Inflammation of the pituitary gland. "They showed that the increases in anti-guanine nucleotide-binding protein G subunit alpha (GNAL) and anti-integral membrane protein 2B (ITM2B) were associated with hypophysitis irAE in both discovery and confirmation cohorts." (PMID 38539558, 2024). "The presence of anti-pituitary, anti-GNAL (guanine nucleotide-binding protein G subunit alpha), and anti-ITM2B (integral membrane protein 2B) autoAbs has been associated with ICI-induced hypophysitis." (PMID 38611115, 2024). "Autoantibodies against guanine nucleotide-binding protein G subunit alpha (GNAL) and integral membrane protein 2B (ITM2B) have been found associated with ICI-induced hypophysitis." (PMID 35432346, 2022). "Using ELISA, baseline anti-GNAL and elevation of both anti-GNAL and anti-ITM2B antibodies during treatment were shown to be associated with hypophysitis in 20 patients and anti-CD74 antibodies with pneumonitis occurrence in 32 patients with solid tumors." (PMID 33643899, 2020). "Autoantibodies against GNAL and ITM2B have been linked to the development of hypophysitis." (PMID 39941803, 2025). "Recently, the guanine nucleotide-binding protein G(olf) subunit alpha (GNAL) and the integral membrane protein 2B (ITM2B) have been identified as targets of autoantibodies in hypophysitis." (PMID 39941803, 2025). "Tahir and co-workers delivered findings of the presence of auto-antibodies against guanine nucleotide-binding protein G (olf) subunit alpha (GNAL) and anti-integral membrane protein 2B (ITM2B) during ICI therapy-induced hypophysitis." (PMID 32824462, 2020).
cerebral amyloid angiopathy (4 papers, 2009 to 2024). "Among its related pathways are HIV Life Cycle and Lipoprotein metabolism, and the most associated diseases include Cerebral Amyloid Angiopathy, Itm2b-Related and Avian Influenza." (PMID 37454083, 2023). "Both of these conditions show cerebral amyloid angiopathy (comprising ITM2B peptide fragment fibrils), which is not a pathognomonic feature of LATE-NC." (PMID 37674727, 2023).
lung carcinoma (4 papers, 2022 to 2024). "In the context of lung cancer, miRNA-143-3p facilitates the proliferation of lung cancer cells by targeting and regulating ITM2B." (PMID 39720726, 2024). "Downregulation of ITM2B has been identified in human lung cancer tissues; therefore, ITM2B appears to play a role as a tumor suppressor gene." (PMID 37760246, 2023). "Exosomal miR‐143‐3p from G‐MDSCs downregulated integral membrane protein 2B and enhanced the PI3K/Akt signalling for lung cancer progression." (PMID 37830387, 2023). "miR-143-3p in G-MDSC-derived exosomes inhibited integral membrane protein 2B (ITM2B) and activated the PI3K/AKT pathway, thus promoting the cell proliferation of lung cancer." (PMID 35634311, 2022).
retinal degeneration (3 papers, 2020 to 2023). Degeneration of the retina. "The results showed that proteins like CST3, C9, and ITM2B, among others, are associated with retinal degeneration while proteins such as COL1A2, IGFBP2, and AGT, among others, are associated with diabetic complications." (PMID 37884923, 2023).
bladder cancer (2 papers, 2021 to 2025). "Similarly, circRNA RB1-ITM2B originates from a read-through transcript of the tumour suppressor RB1 gene into the downstream ITM2B as detected in melanoma, lung and bladder cancers." (PMID 39321865, 2025).
cerebellar ataxia (2 papers, 2021 to 2026). A neurological syndrome characterized by clumsy and uncoordinated movement of the limbs, trunk, and cranial muscles. "ITM2B mutations have been associated with different disorders: mutations leading to longer mutant proteins have been reported in two distinct Alzheimer-like autosomal dominant disorders with early-onset progressive dementia and cerebellar ataxia." (PMID 34446781, 2021).